U8 (U8 small nucleolar RNA )
Synonyms: LOC124900551
Gene: Small nucleolar RNA gene on chromosome 3 (180,542,701 to 180,542,836, forward strand). Ensembl gene ENSG00000201810.
Gene Ontology:
Biological process: RNA processing
Cellular component: nucleolus
Homologues: Orthologues: chimpanzee U8 (99% identical), macaque U8 (93% identical), guinea pig U8 (76% identical). Paralogues in human: U8 (85% identical), U8 (79% identical), U8 (78% identical), U8 (77% identical), U8 (76% identical), U8 (75% identical), U8 (74% identical), U8 (72% identical), U8 (69% identical), U8 (68% identical), U8 (64% identical), U8 (51% identical).